HIF1A (hypoxia inducible factor 1 subunit alpha)
Diseases named in the same sentence as HIF1A in open-access papers (continued):
Sharing a sentence is not in itself a finding about the gene and the disease.
meningioma (12 papers, 2020 to 2025). A generally slow growing tumor attached to the dura mater. "Hypoxia being under the tight control of HIF1A, we demonstrated it to be a hallmark of meningioma progression." (PMID 37601663, 2023). "Some studies have shown an association between the expression of HIF-1α (a key participant in the hypoxia signaling pathway) and meningiomas of different grades." (PMID 37305351, 2023). "Here we demonstrate that KLF4K409Q mutation in meningioma leads to an upregulated HIF-1α pathway, leaves cells susceptible to hypoxia and that this effect can be blocked by mTOR inhibition with Temsirolimus." (PMID 32245394, 2020). "Previous studies have shown an association of HIF-1α expression with different degrees of meningioma and perihematomal edema, and that hypoxia significantly increases glucose uptake and utilization in the tumor cells." (PMID 32908869, 2020). "Similarly, we show that in meningiomas the KLF4K409Q mutation results in an increased HIF-1α activity through impaired HIF-1α degradation." (PMID 32245394, 2020). "Serum HIF-1α levels were significantly higher in GBM patients compared to meningioma patients after RT in this study." (PMID 40512281, 2025). "According to our examination of mRNA expression in patient-derived meningioma primary cells, during the hypoxia induced by CoCl2, in addition to HIF-1α activation, there is AhR upregulation." (PMID 37305351, 2023). "Our findings show active functioning of AhR signaling in meningioma tissue of patients with tumor embolization and crosstalk between HIF-1α and AhR signaling in meningeal cells under hypoxia." (PMID 37305351, 2023). "Because the NcoA2 inhibits proteins of the bHLH/PAS family, such as HIF-1α, ARNT, and AhR, it is likely that in the molecular processes of meningioma ischemic hypoxia, AhR signaling probably plays a more important role than the HIF-1α pathway does." (PMID 37305351, 2023). "Regarding meningioma patients, the mean ± SD of serum HIF-1α was 2.30 ± 0.67 before RT that was decreased to 1.8 ± 0.58 after RT." (PMID 36121548, 2022). "HIF-1α-positive expression in meningioma PTBE grades 0, I, II, and III was 34.4% (22/64), 47.1% (16/34), 54.5% (18/33), and 75.9% (22/29), respectively (Bonferroni-corrected, P = 0.003, α/6 = 0.008)." (PMID 32908869, 2020). "Spearman's correlation analysis revealed a correlation between the expression of GLUT3 and HIF-1α in meningiomas (r = 0.463, P < 0.001)." (PMID 32908869, 2020). "Of the 112 low-grade meningiomas, 48 (42.9%) exhibited a high HIF-1α expression, whereas of the 48 high-grade meningiomas, 30 (62.5%) exhibited a high HIF-1α expression, which was also statistically significant (P = 0.023)." (PMID 32908869, 2020). "One study found that silencing of HIF-3α (an HIF-1α inhibitor) suppresses angiogenesis and proliferation in meningioma." (PMID 33042832, 2020). "Studies have shown that HIF-1α expression is significantly different in meningiomas of different pathological grades and that HIF-1α expression is positively correlated to the malignancy of the meningioma." (PMID 32908869, 2020). "The results of this study indicate a statistically significant difference in the expression of GLUT3 and HIF-1α in meningiomas of different tumor sizes and pathological grades." (PMID 32908869, 2020). "Here we identify a crucial role of the KLF4K409Q mutation in the control of the hypoxic pathway through HIF-1α and uncover novel therapeutic options to specifically treat KLF4K409Q mutated meningiomas." (PMID 32245394, 2020). "GLUT3 and HIF-1α expression in meningiomas was closely related to the tumor size, pathological grade, and PTBE." (PMID 32908869, 2020). "Increased HIF-1α expression in meningiomas is not only known to activate VEGF expression but also triggers the other consequences of hypoxia in meningioma." (PMID 32908869, 2020). "We observed that GLUT3 and HIF-1α expression significantly increased with the size and pathological grade of the meningioma." (PMID 32908869, 2020).
meningioma (continued). "Furthermore, HIF-1α expression was positive in 55.7% of low-grade meningiomas and 84% of high-grade meningiomas." (PMID 40512281, 2025). "Moreover, HIF-1α and VEGF-A are correlated with peritumoral edema, which was demonstrated to be associated with poor prognosis in meningiomas." (PMID 35712491, 2022). "Importantly, TMA-staining of the matched KLF4wt / KLF4K409Q meningioma samples confirmed the increased expression of HIF-1α in KLF4K409Q meningiomas." (PMID 32245394, 2020). "In addition, there was a statistically significant difference in the pattern of expression of GLUT3 and HIF-1α between meningiomas with different severity of peritumoral edema." (PMID 32908869, 2020). "In this study, we investigated whether the expression of GLUT3 and HIF-1α in meningiomas is related to the tumor size, Ki-67, PTBE, and pathological grade." (PMID 32908869, 2020). "After RT, HIF-1α serum levels were significantly enhanced than before RT in GBM patients, whereas they decreased in meningioma patients." (PMID 40512281, 2025). "Compared with healthy volunteers, significant increases in serum HIF-1α were shown before RT in both GBM and meningioma subgroups." (PMID 40512281, 2025). "In this work, the status of HIF-1α- and AhR-dependent signaling pathways was investigated in World Health Organization (WHO) grade 1 meningioma and patient-derived tumor primary cell culture under hypoxic conditions." (PMID 37305351, 2023). "Considering that TAMs promote meningioma growth, while HIF-1α and VEGF stimulate tumor neoangiogenesis, these results confirmed the more aggressive biological behavior of convexity meningiomas, compared with SBMs." (PMID 35892898, 2022). "In the current study, both HIF-1α and VEGF were significantly decreased after RT when compared to before RT in meningioma patients." (PMID 36121548, 2022). "HIF-1α activates VEGF transcription via the PI3K/Akt signaling pathway, up-regulating VEGF expression and promotes endothelial cell proliferation in meningioma." (PMID 33042832, 2020). "The decrease in AhR and HIF-1α mRNA levels in embolized meningiomas did not alter either HIF-1α or AhR protein amounts, thereby indicating a sufficiently high constitutive level of these proteins." (PMID 37305351, 2023). "The decrease in AhR and HIF-1α mRNA levels in embolized meningiomas did not lead to a change in either HIF-1α or AhR protein amounts, thereby indicating a sufficiently high constitutive level of these proteins." (PMID 37305351, 2023). "A large cohort study of 263 patients with meningiomas found that upregulated levels of HIF-1α and VEGF-A could significantly predict the recurrence of meningiomas." (PMID 35712491, 2022). "Moreover, expression of HuR, HIF-1α, and Glut-1 was associated with OS, but no associated with PFS of meningioma patients." (PMID 38758750, 2024). "As revealed by our analysis of mRNA expression in samples of meningioma tissue subjected to hypoxic ischemic preconditioning, the expression of HIF-1α and its target genes (VEGF-A, c-Myc, and GLUT1) is not affected by this procedure, whereas AhR, ARNT, and NcoA2 expressions significantly decreases." (PMID 37305351, 2023). "We documented a heterogeneous pattern of expression of HIF-1α and its target genes in both nonembolized and embolized meningiomas; this finding may be due to the small sample size and different histological subtypes of the tumors under study." (PMID 37305351, 2023). "mRNA expression of HIF-1α, AhR, ARNT, and HIF-1α and AhR target genes did not change when meningioma cells were incubated with B[a]P (AhR agonist)." (PMID 37305351, 2023). "In particular, due to the small number of cases with certain meningioma subtypes, we were not able to explore GLUT3 and HIF-1α expression patterns across all subtypes of WHO grade meningiomas." (PMID 32908869, 2020).
nonalcoholic fatty liver disease (12 papers, 2018 to 2025). "In addition, a new HIF1α/PTEN/NF-κBp65 signaling pathway has been identified recently in non-alcoholic fatty liver disease in which HIF-1α promoted fibrosis via PTEN/ p65." (PMID 35870078, 2022). "In nonalcoholic fatty liver disease, hypoxia induces HIF-1α accumulation, and consequently, PTEN expression is reduced, exacerbating liver fibrosis in nonalcoholic fatty liver disease." (PMID 35280516, 2022). "In non-alcoholic fatty liver disease (NAFLD), miR-122 targets HIF-1α, vimentin, and mitogen-activated protein kinase kinase kinase 3, which regulate steatosis." (PMID 34943825, 2021).
retinal degeneration (12 papers, 2008 to 2025). Degeneration of the retina. "A number of investigators have proposed that retinal hypoxic preconditioning, which leads to HIF1α induction, morphologically and functionally protects retinal cells against light-induced retinal degeneration." (PMID 22432009, 2012). "Hypoxic preconditioning stabilizes the transcription factor HIF-1α in the retina and strongly protects photoreceptors in an animal model of light-induced retinal degeneration." (PMID 18261226, 2008). "Similar problems may be seen in exploiting other HIF-1α targets for treating retinal degeneration." (PMID 28289375, 2017). "Concerning DP, MBD2 was involved in the formation of the eye, interacting both with HK2 and HIF1A, while PIWIL4 displayed an interaction with DICER1, which was involved in retinal degeneration." (PMID 37359372, 2023). "HDAC4 overexpression in a mouse model of retinal degeneration prolonged photoreceptor survival, which was attributed to the activity of HDAC4 in the cytoplasm and at least partly relied on the activity of HIF-1α." (PMID 34057022, 2021). "According to the results in ARPE-19 cells that KC7F2 could reduce the HIF1α expression induced by HTRA1 and halt the cellular senescence, we explored whether KC7F2 could improve retinal degeneration induced by NaIO3in-vivo." (PMID 37316948, 2023). "Lack of HIF1A (together with HIF2A) in cones also did not affect protection against light-induced retinal degeneration by hypoxic preconditioning." (PMID 31695081, 2019). "We hypothesized that stabilized HIF1A, and not other Vhl targets, might promote retinal degeneration and neovascularization in coneΔVhl mice." (PMID 29514656, 2018).
Sleep apnea (12 papers, 2012 to 2025). An intermittent cessation of airflow at the mouth and nose during sleep is known as sleep apnea. "Our results increase the understanding of the genetic architecture of sleep-disordered breathing and highlight associations in genes that modulate lung development, inflammation, respiratory rhythmogenesis, and HIF1A-mediated hypoxic response." (PMID 34446064, 2021). "HIF1a signaling is upstream of molecular aberrations that are linked to neurocognitive defects, positioning HIF1a signaling as a good target for potential therapies for sleep apnea." (PMID 33273035, 2020). "In a large multicenter cohort of patients being diagnosed with CM, the expression of HIF-1α in the tumoral lesions is independently associated with nocturnal IH measures of sleep disordered breathing severity." (PMID 29755400, 2018). "Interestingly, sleep apnea has been associated with HU and incident gout through HIF-1α activation." (PMID 39872146, 2024). "Therefore, it was unknown whether HIF1a expression is altered specifically in the hippocampus following IH exposure, and if so, whether HIF1a-dependent signaling is responsible for neurocognitive defects associated with sleep apnea." (PMID 33273035, 2020). "This study has further consolidated the role of HIF-1α activation under hypoxic conditions in the pathogenesis of HU, such as sleep apnea and high altitude." (PMID 39872146, 2024). "In chronic intermittent hypoxemia (CIH), such as occurs in sleep apnea, it differs from continuous hypoxia in the activation of HIF-1α." (PMID 34068590, 2021). "Comparisons between the groups with high and low expression of hypoxia inducible factor (HIF)-1α in relation to sleep-disordered breathing variables and intermittent/continuous hypoxia indicators." (PMID 29755400, 2018). "Suggestive associations of symptoms of sleep apnea were observed with 11 rare variants (located in KANK2, LCN6, TRAF3, PLEK, HIF1A, SLC45A3, ERCC1/CD3EAP, MRGPRE, GRAMD4, TYW5, CST5)." (PMID 29093733, 2017). "In mice, the cyclic oxygen deprivation observed in sleep apnea induces oxidative stress and activation of HIF-1α, which stimulates a cascade of inflammatory signaling, nitric oxide generation, angiogenesis, and apoptosis in the lung and liver." (PMID 23226929, 2012). "Moreover, HIF1A has also been identified as a mediator of the FPT-activated angiogenesis in sleep apnea." (PMID 39457593, 2024). "HIF-1α levels were reported to increase in COPD patients in an amount proportional to severity and increased in sleep apnea with hypoxemia." (PMID 34068590, 2021). "In sleep apnea models, elevated HIF-1α led to a 2-fold increase in ROS and severe NMDA receptor-dependent LTP impairment, while heterozygous HIF-1α knockout mice exhibited no LTP deficits." (PMID 41202111, 2025).
adenoma (11 papers, 2008 to 2025). A neoplasm arising from the epithelium. "The heterozygous variant (C/T) of the HIF1A gene was significantly more common (p=0.02) in patients with invasive adenomas compared to the control group: 25% (n=13) and 9.8% (n=8), respectively." (PMID 41014611, 2025). "HIF-1α mRNA and/or protein is detected in both adenomas and CRCs, being more commonly expressed in adenocarcinomas than in adenomas, as a number of immunohistochemical studies indicate." (PMID 32183342, 2020). "A significantly higher HIF-1α expression was noted in adenocarcinomas in comparison to adenomas (P < 0.0004)." (PMID 24153191, 2013). "Statistical analysis using Mann-Whitney test demonstrated a significantly higher HIF-1α expression in adenocarcinomas than in adenomas (P = 0.0004)." (PMID 24153191, 2013). "In all the cases with positive reaction (90% adenocarcinomas and in 86% adenomas) a nuclear-cytoplasmic HIF-1α expression was noted." (PMID 24153191, 2013). "The study aimed at examining hypoxia-inducible factor (HIF)1α expression in adenocarcinomas and adenomas in bitches in regard to tumour malignancy grade, proliferation, apoptosis and vascularisation." (PMID 24153191, 2013). "We conclude that overexpression of HIF-1α can occur early in colorectal carcinogenesis in both the traditional (adenoma-carcinoma seqence) and serrated pathway." (PMID 18983642, 2008). "In the urethane-induced NSCLC mouse model, we compared the levels of HIF-1α protein in the small lung adenomas of multiple IKKα WT control IKKα+/+:Sftpc-CreERT2 mice with the amounts of HIF-1α expressed by the unique class of large adenomas in the experimental IKKαf/f:Stpc-CreERT2 mice." (PMID 31792060, 2019). "Finally, as observed with the mouse IKKαKO large adenomas, two selected direct HIF-1α target genes (Slc2a1 and PDK1) were also found to be up-regulated by quantitative qRT-PCR in independent IKKαKD H1437 tumor xenografts." (PMID 31792060, 2019). "In light of these observations, we next investigated if the higher levels of HIF-1α protein in the lungs and the large adenomas of the urethane-treated experimental IKKαf/f:Sftpc-CreERT2 mice also resulted in the up-regulation of specific direct HIF target genes." (PMID 31792060, 2019). "Our study aimed at demonstration of HIF-1α protein expression and determination of its intensity in the most frequently manifested malignant and benign mammary tumours of epithelial origin (adenocarcinomas and adenomas) in bitches." (PMID 24153191, 2013). "Interestingly, in colorectal carcinogenesis, the adenoma-carcinoma sequence was reported to be associated with induction of HIF-1α in premalignant lesions as well as with dysplasia; HIF-2α was also reported to promote progression from adenoma to carcinoma." (PMID 24130777, 2013). "So far, only one study reported detection of HIF-1α m-RNA in four of nine investigated adenomas." (PMID 18983642, 2008). "HIF-1α induced by hypoxia or apoplexy inside the adenoma might be the initiating factor of invasive transformation, followed with angiogenesis for overexpressed VEGF, EMT for overexpressed PTTG, degradation of ECM for overexpressed MMPs, creating a suitable microenvironment within the tumor." (PMID 30733705, 2019). "Similarly in our study we have demonstrated a pronounced positive correlation between expression of HIF-1α and density of microvessels both in a malignant (adenocarcinoma) and benign (adenoma) tumours, even if in the latter case the correlation has shown a slightly lower level." (PMID 24153191, 2013). "It should be noted that over 9% of adenocarcinomas and over 13% of adenomas manifested no HIF-1α expression." (PMID 24153191, 2013). "Pirc rats harboring adenomas/tumors had a significant increase in glycolytic markers in their noninvolved colorectal mucosa compared to Pirc rats without adenomas/tumors, including HIF1α (1.45 fold, p = 0.018), GLUT1 (1.35 fold, p = 0.003), PKM2 (1.33 fold, p = 0.05) and LDHA (1.4 fold, p = 0.003)." (PMID 28423551, 2017).
adenoma (continued). "Immunohistochemistry and Western blot is used to analyse HIF-1α expression in normal colonic mucosa, hyperplastic polyps (HPP), sessile serrated adenomas (SSA), low-grade (TA-LGD) and high-grade (TA-HGD) traditional adenomas as well as in non-metastatic and metastatic colorectal adenocarcinomas." (PMID 18983642, 2008).
Crohn disease (11 papers, 2018 to 2025). A gastrointestinal disorder characterized by chronic inflammation involving all layers of the intestinal wall, noncaseating granulomas affecting the intestinal wall and regional lymph nodes, and transmural fibrosis. "In Crohn’s disease, however, Th17-cells display lower AhR expression and higher levels of hypoxia-inducible-factor-1alpha (HIF-1α), known to inhibit AhR levels and signaling." (PMID 30691212, 2019). "It has been reported that HIF-1α overexpression modification enhances immunomodulation in dental MSCs and improves the healing properties of extracellular vesicles by suppressing activated T-cells in Crohn’s disease." (PMID 36979804, 2023). "Current research has implicated a close correlation between key ferroptosis-related genes such as TIMP1, CAV1, CD44, HIF1A, and IFNG, and immune infiltration in Crohn’s disease." (PMID 40687427, 2025). "In Crohn’s disease, the altered response of Th17 cells to UCB also derives from high levels of HIF-1α that, in concert with a hypoxic environment, limits the responsiveness of these cells to AhR activation." (PMID 36131123, 2022). "Furthermore, in Crohn disease, another IBD, increased HIF-1α protein plays a major role in adherent-invasive E. coli (AIEC) induced inflammatory disorders of the gastrointestinal tract." (PMID 33808042, 2021). "The reason for this poor responsiveness relies, at least to some extent, on aberrantly high levels of inflammation-induced HIF-1α that induces drug transporters like multidrug resistance 1 (MDR1) and multidrug resistance protein 4 (MRP4) in Th17 cells derived from Crohn's disease patients." (PMID 33553158, 2020).